ITGB1 (integrin subunit beta 1)
Diseases named in the same sentence as ITGB1 in open-access papers (continued):
Sharing a sentence is not in itself a finding about the gene and the disease.
tumor (continued). "Our study demonstrates that the Piezo1/ITGB1 axis enhances the rapid proliferation and antiapoptotic capabilities of tumor cells through enhancing Ca2+ and modulating key proteins such as YAP, α‐SMA, and so on." (PMID 40667648, 2025). "On the other hand, our analysis identified ITGB1, ITGA5, and ITGA6 as key integrins significantly associated with poor prognosis in HNSC, underscoring their role in driving tumor aggressiveness and therapeutic resistance." (PMID 40021759, 2025). "NONO knockdown significantly downregulated the core clock gene PER2 and the oncogene DEC1 and markedly reduced tumor-cell expression of key fibroblast-signal receptors, including ITGB1, SDC1, and CD47." (PMID 41174721, 2025). "In our previous reports, MCP inhibited downstream signaling pathways of integrin β1 (ITGB1), reducing the effectiveness of tumor-driving genes." (PMID 40600063, 2025). "To explore their functional relevance, we generated ITGA5/ITGB1 double knockdown cell lines and assessed their impact on tumor growth in vivo." (PMID 40770810, 2025). "The suppression of neural invasion and tumor progression of ITGB1 blockade was reproduced in orthotopic PDAC models." (PMID 40923379, 2025). "In cancers like breast and pancreatic cancer, dysregulation of ITGB1 has been shown to promote immune evasion by modulating immune cell trafficking and facilitating tumor invasion." (PMID 40817072, 2025). "Unlike natalizumab (which targets ITGA4 and prevents the ability of α4β4 or α4β7 integrin to bind VCAM-1), a single treatment targeting ITGB1 would prevent tumor cells from adhering to a number of ECM ligands, including fibronectin, collagen IV, and laminin." (PMID 38279122, 2024). "Cancer metastasis is a complex multi-step process that requires cancer cells to invade from their primary tumor site, survive in the circulation, and eventually colonize on nearby or distant organs: ITGB1 is involved in each step of this process." (PMID 38279122, 2024). "Vacuolar-ATPase inhibitors have been demonstrated to control the anti-apoptotic capacity of several tumor cells by lowering the ITGB1 activity." (PMID 38279122, 2024). "OS2966, a neutralizing ITGB1 monoclonal antibody, attenuates aggressive tumor phenotypes in vitro and inhibits growth of antiangiogenic therapy-resistant tumor xenografts in vivo, constituting a potential therapeutic opportunity." (PMID 38279122, 2024). "Clinically, a significant correlation of high IER2/ITGB1 expression with tumor aggressive phenotype and poor patient survival is observed." (PMID 39207055, 2024). "Our analyses unveiled that high expression of ITGB1 was positively correlated with tumor invasion into surrounding muscle tissues and advanced AJCC staging." (PMID 39207055, 2024). "ITGB1 is frequently upregulated in OC and increases tumor cell invasion by increasing the expression of MMP-2 and MMP-9." (PMID 38279122, 2024). "IER2 also induces expression of ERS‐CAF marker genes and results in production of a pro‐tumorigenic paracrine GMFG signaling, which exert its biological function via directly binding to ITGB1 on tumor cells." (PMID 39207055, 2024). "ITGB1 inhibition attenuates tumor malignant progression, which can be partially reversed by exogenous GMFG intervention." (PMID 39207055, 2024). "It is demonstrated that the over‐activated Piezo1/integrin β1 (ITGB1) signaling axis significantly facilitates tumor‐targeted delivery of R11 peptides via macropinocytosis." (PMID 39258781, 2024). "The role of ITGB1 in the tumor microenvironment (TME) and its interaction with ITEM remains to be further confirmed." (PMID 38402311, 2024). "For example, 3D-cultured colorectal cancer cells can promote tumor dedifferentiation through an ITGB1/PFK-dependent mechanism." (PMID 39239559, 2024). "It has also been observed that some tumor-suppressor transcription factors are negatively correlated with ITGB1 expression, further providing evidence of ITBG1′s tumor-promoting effect." (PMID 38732562, 2024).
tumor (continued). "In general, these results suggest that ITGB1 can play a significant role in the biological process of tumor proliferation or apoptosis." (PMID 38279122, 2024). "Further post‐hoc analysis validated that ITGB1 was truly significantly up‐regulated in tumor cells after the exogenous GMFG intervention." (PMID 39207055, 2024). "Our work suggested the involvement of the Piezo1/ITGB1 signaling axis in the tumor‐targeted delivery of R11 peptides." (PMID 39258781, 2024). "We further demonstrate that blocking ANG-2/ITGB1 signaling suppressed tumor cell invasion and the formation of metastasis in an autochthonous SCLC mouse model." (PMID 38775153, 2024). "Consistently, ITGB1 has been reported to be involved in lymph node, tumor, and peritoneal metastasis of OC." (PMID 38814534, 2024). "Subsequent qPCR and WB analysis evidenced that exogenous GMFG treatment markedly induced ITGB1 expression on tumor cells." (PMID 39207055, 2024). "ITGB1 expression significantly correlates with tumor stage in patients and is increased in matched SCLC liver metastases." (PMID 38775153, 2024). "Ki67 expression in tumors was determined by immunohistochemistry, and the proportion of Ki67-positive cells in tumors was decreased in tumor-bearing mice established by OCSCC cells with BMI1 or ITGB1 knockdown." (PMID 38254031, 2024). "Our analyses indicated that GMFG exerted its biological function through interaction with ITGB1 on tumor cells." (PMID 39207055, 2024). "Further, QIF experiments confirmed that ITGB1 expression on tumor cells was significantly correlated with tumor aggressiveness and patient clinical outcomes." (PMID 39207055, 2024). "Tumour targets were enriched for genes involved in cell proliferation, G1/S transition, and inhibition of apoptosis; for example, BIRC5 activated by ITGB1 from the tumour and stroma." (PMID 38890455, 2024). "Studies have found that serum linc-ITGB1 levels are significantly correlated with tumor size and distant tumor metastasis in HCC." (PMID 38334963, 2024). "Noticeably, our analysis also disclosed that IER2+ ERS‐CAF displayed the most proximity to ITGB1+ tumor cells, mainly enriched within a 60 μm radius of ITGB1+ tumor cells." (PMID 39207055, 2024). "Mechanistically, we show that ITGB1 signaling in SCLC tumor cells induced an EMT-like phenotype via FAK/SRC signaling and that ITGB1 fulfilled essential roles in intra- and extravasation of SCLC cells." (PMID 38775153, 2024). "Studies showed that micro-RNAs play crucial functions in tumor invasion, propagation, and the expression of ITGB1, reducing tumor cells' ability to attack and metastasize." (PMID 38739758, 2024). "Among them, SPP1 was significantly upregulated on macrophages in ROIs with high tumor ITGB1 expression, and the expression of these two genes was significantly positively correlated by analyzing the DSP data." (PMID 39207055, 2024). "Concordantly, a subcutaneous tumor model of HCC showed that ITGB1 knockdown led to a significant reduction in tumor incidence rate." (PMID 38956074, 2024). "The combination of targeted ITGB1 and other anti-tumor medicines (radiotherapy, chemotherapy, and targeted therapy), has the potential to overcome tumor resistance." (PMID 38279122, 2024). "In this study, compared to non-anoikis-mediated CD8 + T cells, more pronounced intercellular communication was observed between anoikis-mediated CD8 + T cells and MES-like tumor cells, especially in the ITGB1 + CD8 + T cell-C1 cluster." (PMID 39143438, 2024). "We identified ITGB1, one of the hub genes, as having prognostic effects linked to CAF-mediated tumor progression." (PMID 38347596, 2024). "We found that the expression of SPP1/ITGB1 signaling was more pronounced in the regions of tumor cells proximal to TAMs." (PMID 39207055, 2024). "On the protein level, SCLC cell lines obtained from metastatic sites displayed a higher ITGB1 expression than cell lines obtained from the primary tumor site of the lung." (PMID 38775153, 2024).
tumor (continued). "ITGB1 is integrin, which can affect tumor process by regulating angiogenesis, apoptosis, and metastasis." (PMID 38383330, 2024). "Of note, ITGB1 significantly correlated with advanced UICC tumor stage and epithelial-to-mesenchymal transition (EMT), which is highly dynamic and frequently observed in progressing tumors." (PMID 38775153, 2024). "Taken together, ANG-2/ITGB1 signaling promotes tumor metastasis in SCLC that is therapeutically vulnerable." (PMID 38775153, 2024). "In particular, ligand-receptor pair analysis revealed that the SPP1 signal was mainly involved in the interaction among tumor-associated macrophage (TAM), T cells, and malignant cells via SPP1–CD44 and SPP1–(ITGA5 + ITGB1) ligand-receptor pairs." (PMID 38282028, 2024). "SPP1 was mainly involved in the interaction among tumor-associated macrophages, T cells, and malignant cells via SPP1–CD44 and SPP1–(ITGA5 + ITGB1) ligand-receptor pairs." (PMID 38282028, 2024). "This information demonstrates a possible role for ITGB1 in controlling the neoplasm microenvironment (TME)." (PMID 38402311, 2024). "The analysis of scRNA-seq data showed that SPP1 was highly expressed in malignant cells and HPC-like cells and mainly involved in the interaction among tumor-associated macrophage, T cells, and malignant cells via SPP1–CD44 and SPP1–(ITGA5 + ITGB1)." (PMID 38282028, 2024). "For the treatment of ITGB1, additional research is required to identify its precise ligand or to inhibit its activity through different pathways to achieve tumor suppression." (PMID 38279122, 2024). "Regarding the clinical application, our data strongly indicate that tumor cell–dependent ANG-2/ITGB1–mediated invasion and metastasis is a highly promising therapeutic target to prevent the formation of liver metastasis in patients with SCLC." (PMID 38775153, 2024). "These CAFs were co‐cultured with U‐CH1 or UM‐Chor1 cells featuring ITGB1 knockdown to observe the alterations in tumor cell behavior and ITGB1 signaling." (PMID 39207055, 2024). "Here, FGFR2 and ITGB1 expression levels were both significantly decreased in tumour samples (log2FC=-0.78, p = 0.006, and log2FC=-0.54, p < 0.00001, respectively)." (PMID 37191822, 2023). "Researchers found that ITGB1 was able to influence cell function and thus influence tumor development and progression." (PMID 37007126, 2023). "The relationships between ITGB1 expression and clinicopathological features, patient prognosis, activation of the Wnt/β‐catenin signaling pathway, and tumor immunosuppressive factors were also explored." (PMID 35864742, 2023). "Some studies have also demonstrated that ITGB1 was involved in a variety of activities, including embryonic development and blood vessel, as well as tumor metastasis and angiogenesis." (PMID 37007126, 2023). "ITGB1 expression was shown to be significantly stronger in tumor tissue than in adjacent normal gastric mucosa, while stronger expression was also observed in poorly differentiated tumor tissue that had penetrated the serosa layer." (PMID 37667169, 2023). "ITGA5 is a member of the integrin alpha chain family and combines with ITGB1 to form integrin α5β1, which has been demonstrated to engage in tumor cell adherence." (PMID 38248716, 2023). "Several studies have revealed that the repression of ITGB1 expression can attenuate tumor metastasis and invasiveness." (PMID 37004120, 2023). "This WAVE2/miR-29/ITGB1 signaling axis is critical for the regulation of tumor growth and metastasis of TNBC tumors." (PMID 36968231, 2023). "H&E staining showed that ITGB1-blocking antibody treatment resulted in less tumor cell infiltration in popliteal LNs." (PMID 36632222, 2023). "ITGB1 expression in GC was significantly correlated with patient's age (p < 0.001), tumor differentiation (p = 0.001), and Lauren's classification (p < 0.001)." (PMID 35864742, 2023).
tumor (continued). "Collagen such as COL1A1/COL1A2/COL3A1 can change the resistance of tumor cells by interacting with the ITGB1 integrin, as reported for other cancers." (PMID 36460803, 2023). "We confirmed these results by knocking down ITGA5 or ITGB1, following which the ability of NETs to adhere to tumor cells was greatly reduced." (PMID 37958984, 2023). "We observed varying degrees of decrease in the fluorescence intensity of Oct4, Sox2, Aldh1a1, Epcam, and Itgb1 in tumor tissues formed by 66cl4-shSix1 KD1-luc and 66cl4-shSix1 KD2-luc compared to those formed by 66cl4-SCR-luc." (PMID 38031089, 2023). "Meanwhile, these genes of phosphorylation related with ITGB1 also facilitated or inhibited the occurrence and development of tumor." (PMID 37007126, 2023). "Animal experiments also showed tumor volume and weight decreased after X-ray irradiation in ITGB1 depletion groups." (PMID 38065955, 2023). "High levels of ITGB1 resulted in reduced OS rates, worse pathology G-staging and tumor T-staging which is indicative of clinical progression and consistent with previous reports." (PMID 37667169, 2023). "ITGB1 are membrane receptors involved in cell adhesion, embryogenesis, homeostasis, tissue repair, immune response, and metastatic diffusion of tumor cells." (PMID 37069190, 2023). "The positive rate of ITGB1 in GC tumor tissues was 61.4% (258/420), which was much higher than that in the normal gastric mucosa (33.3%, 9/27)." (PMID 35864742, 2023). "Overall, this study revealed that ITGB1 was a protumorigenic gene and regulated tumor metabolism and cuproptosis in DGC." (PMID 37007126, 2023). "As such, we identified a novel WAVE2/miR-29/ITGB1 signaling axis that regulates TNBC tumor growth and metastasis." (PMID 36968231, 2023). "Meanwhile, we extracted tumor genomic characteristics from DGC, and found that ITGB1 was associated with tumor mutation load, dMMR signature, and copy number variations." (PMID 37007126, 2023). "ITGB1 is one of the upstream molecules of the Wnt/β‐catenin signaling pathway and is correlated with tumor immune suppression." (PMID 35864742, 2023). "Although miR-183 has a well proven oncogenic function in PrCa, the tumor suppressor role of ITGB1 suggested by our results is contradictory with previous findings." (PMID 35202085, 2022). "Previous studies have shown that integrin β1 (ITGB1) is overexpressed in tumor cells and is involved in angiogenesis, tumor progression, and metastasis." (PMID 36178365, 2022). "The role of ITGB1 in tumor progression has been demonstrated for several tumor entities, including lung, prostate, breast, and colorectal cancer." (PMID 36456612, 2022). "ITGB1 was reported to promote cell invasion and tumor metastasis of PDAC cells, thus ITGB1 is a therapeutic target for the treatment of PDAC." (PMID 35275973, 2022). "RBP2 directly binds to the integrin b1 (ITGB1) promoter and is involved in tumor migration and invasion." (PMID 35013450, 2022). "In vitro, THBS4 also promotes tumor progression by interacting with ITGB1 via the FAK/PI3K/AKT pathway." (PMID 36241983, 2022). "The stromal tissue of the tumor samples was stained uniformly for ITGB1 in all cases, with a slightly weaker intensity than that of the surrounding normal pancreatic tissue." (PMID 35648752, 2022). "In this study, deterioration of OS and DFS was observed in the high ITGB1 expression group of tumor cells." (PMID 35648752, 2022). "Integrins, including ITGB1, are a family of heterodimeric glycoproteins expressed on tumor cells and the surface of activated endothelial cells." (PMID 35629036, 2022). "In the past, the focus was on the analysis of an altered extracellular matrix within the tumor and thus a modified signal transduction after bidding of ITGB1 expressing tumor cells to the ECM26." (PMID 36456612, 2022).
tumor (continued). "In this group, patients with ITGB1 expression in the tumor showed a median OS of 10.2 months (95% CI 1.9–41.7 months) compared to a median OS of 31.4 months (95% CI 21.1–144.2 months, P = 0.008) in the group without ITGB1 expression." (PMID 36456612, 2022). "Cases displaying high ITGB1/low CDH1 expression were strongly associated with diffuse type gastric cancer and increased tumour grade." (PMID 34486077, 2022). "Intriguingly, we found that ITGB1 protein expression levels were significantly lower in ESCC tumor tissues than in normal tissues, in accordance with previously reported data in ESCC proteomics, while the exact opposite was true for fucosylated ITGB1 levels." (PMID 35752862, 2022). "Intriguingly, no significant drugs resistance was observed in ITGB1+ cells or collagen cultured ITGB1- tumor cells, whereas ITGB1+ cells cultured in 3D collagen gels revealed obvious 5-FU resistance." (PMID 34319913, 2021). "Our results further disclosed the role of type I collagen in tumor progression, which is dependent on collagen binding integrin receptor ITGB1." (PMID 34319913, 2021). "MicroRNA-493-5p (miR-493-5p) was a tumor repressor in NSCLC progression by targeting integrin beta-1 (ITGB1) or DEAD-box helicase 5 (DDX5)." (PMID 34537072, 2021). "Consistently, we also observed an upregulated expression of ITGB1 in HCC tumor tissues as compared with matched non-tumor tissues." (PMID 34977001, 2021). "In agreement with TCGA data, we observed a prominent increase in ITGB1 expression in HCC tumor tissues as compared to the normal peritumoral tissues." (PMID 34977001, 2021). "In our study, we provided evidence that type I collagen served as fundamental component in extracellular matrix to facilitate the tumor progression through an ITGB1 dependent manner." (PMID 34319913, 2021). "MicroRNA-29c (miR-29c) by targeting integrin subunit beta 1 (ITGB1) has a role in tumor inhibition in GC." (PMID 34337048, 2021). "ITGB1 is a member of the integrin family and is involved in regulating cells adhesion, metastasis and growth of tumor cells." (PMID 34326374, 2021). "Based on the TCGA database and clinical tumor tissues analysis, we observed abundant type I collagen expression in tumor tissues and poor overall survival in gastric patients with high integrin β1 (ITGB1) expression." (PMID 34319913, 2021). "It has been previously documented that the expression level of ITGB1 in HCC tumor tissues was significantly higher than that in peritumoral tissues." (PMID 34977001, 2021). "Microarray database analysis collected from NCBI showed that tumor cells isolated from bone marrow have fewer copy numbers of ITGA2 and ITGB1 compared to primary tumor cells or circulating tumor cells." (PMID 34199096, 2021). "More importantly, rapid colony growth was observed in ITGB1 positive cancer cells, indicating that ITGB1 positive tumor cells possessed proliferative characteristics in the presence of collagen." (PMID 34319913, 2021). "Herein, we demonstrated that ITGB1 enhanced HCC tumor progression via PXN/YWHAZ/AKT signaling pathways, which confers an increased growth ability to HCC tumors." (PMID 34977001, 2021). "At the same time, ITGB1 has been found to promote tumor resistance to anti-cancer drugs such as bevacizumab, erlotinib and gefitinib." (PMID 34556089, 2021). "Then, the predicted function and mechanisms of ITGB1 were verified in primary tumor cells derived from tissue specimens of three HCC patients as well as in primary tumor cell-derived xenograft model." (PMID 34977001, 2021). "ITGB1-OE has been extensively reported to be able to promote tumor metastasis and progression in various types of cancers." (PMID 34277426, 2021). "Stemming from in vitro findings, we became interested in evaluating the influence of ITGB1 on HCC tumor growth." (PMID 34977001, 2021).